B2M (beta-2-microglobulin)
Diseases named in the same sentence as B2M in open-access papers (continued):
Sharing a sentence is not in itself a finding about the gene and the disease.
Anxiety (1 paper, 2018). Intense feelings of nervousness, tension, or panic often arise in response to interpersonal stresses. "In the present study, we investigated whether B2M causes depressive- and anxiety-like behaviors." (PMID 29795686, 2018). "On the basis of these researches, it is logical to further hypothesize that B2M may contribute to anxiety-like behaviors in rats." (PMID 29795686, 2018). "Our data suggest that B2M play a critical role in the depressive- and anxiety-like behaviors." (PMID 29795686, 2018). "Hence, we investigated whether B2M directly induces depressive- and anxiety-like behaviors in rats." (PMID 29795686, 2018). "We found that B2M induces depressive-like behaviors in the rats of TST, FST, NSFT and that B2M exerts anxiety-like effect in the rats of EMPT." (PMID 29795686, 2018). "Thus, we speculated that B2M may induce depressive- or anxiety-like behaviors." (PMID 29795686, 2018). "Therefore, it is worth to investigating whether B2M leads to depressive- or anxiety-like behaviors." (PMID 29795686, 2018).
arterial disease (1 paper, 2025). "Concurrent studies have established a correlation between B2M and arterial disease, as well as vascular structural changes, and have identified an association with inflammatory responses." (PMID 40837565, 2025).
bladder transitional cell carcinoma (1 paper, 2025). The most common morphologic subtype of urinary bladder carcinoma (over 90% of cases).
brain tumors (1 paper, 2024). "On the one hand, intracellular B2M was abnormally upregulated in brain tumors and regulated tumor microenvironments and progression." (PMID 38743119, 2024). "Furthermore, the levels of B2M in the CSF of CNS lymphoma patients was found to be significantly higher than those with GBM and other brain tumors." (PMID 38743119, 2024).
bronchiectasis (1 paper, 2025). Segmental, irreversible dilation of the bronchial tree resulting in the accumulation of secretions which leads to obstruction. "We found that chronic necrotizing granulomatous skin lesions and childhood-onset bronchiectasis were common but not universal clinical features of TAP1, TAP2, TAPBP, and B2M deficiency." (PMID 41298860, 2025).
brucellosis (1 paper, 2024). Brucellosis is a bacterial infection that spreads from animals to people via unpasteurized dairy products or by exposure to contaminated animal products or infected animals. "In brucellosis patients, the expression levels of many typical IFN‐γ/IFN‐I response genes, including IFITM3, B2M, GBP1, IRF1, IFI30, IFNGR2, and so forth, were higher than those in controls." (PMID 39135683, 2024). "In line with this, the enrichment of genes linked to the ‘interferon‐gamma response’ pathway (e.g., STAT1, IFNG, IRF1, B2M, GAPDH) was also consistently observed in brucellosis patients." (PMID 39135683, 2024).
Burkitt lymphoma (1 paper, 2022). A rare form of malignant mature B-cell non-Hodgkin lymphoma. "The control Burkitt's lymphoma cell line DAUDI was found having the same missense mutation ATG to AGG as previously documented 27, while the DLBCL cell line LY10 was negative for B2M gene mutation." (PMID 36606194, 2022).
cardiac arrest (1 paper, 2008). Cessation of breathing and/or cardiac function. "B2m turned out to be the most variable candidate reference gene, being about 2-fold upregulated in the cardiac arrest treatment groups." (PMID 18505597, 2008).
cerebral malaria (1 paper, 2019). A sequestration of Plasmodium falciparum in the brain, which can cause coma and/or seizures. "Different studies have consistently shown the requirement for T lymphocytes in the pathogenesis of cerebral malaria by demonstrating that infection in mice deficient in beta-2-microglobulin gene as well as mice lacking functional CD8+ T cells are resistant to experimental cerebral malaria." (PMID 30873136, 2019).
clear cell renal carcinoma (1 paper, 2017). A malignant epithelial neoplasm of the kidney characterized by the presence of lipid-containing clear cells within a vascular network. "Ppia, was optimal candidate (along with PRS13) in clear cell renal carcinoma as compared to classical genes such as ACTB, GAPDH, 18s or B2m." (PMID 28591185, 2017).
CNS lymphoma (1 paper, 2024). "Besides, in both univariate and multivariate Cox analyses, plasma B2M levels in CNS lymphoma patients was also found to be associated with prognosis." (PMID 38743119, 2024). "Therefore, CSF B2M levels hold promise as an adjunctive diagnostic indicator for CNS lymphoma." (PMID 38743119, 2024). "And mutations in the B2M leading to decreased or absent B2M expression in CNS lymphoma might be a crucial factor, which, in turn, promoted tumor cells to evade immune surveillance." (PMID 38743119, 2024). "Interestingly, levels of serum B2M in patients with CNS lymphoma were also higher than that in non-CNS lymphoma patients." (PMID 38743119, 2024).
colorectal adenocarcinoma (1 paper, 1987). The most common type of colorectal carcinoma. "Expression of HLA antigens and beta 2-microglobulin was studied by immunoperoxidase staining of frozen sections of 9 mucinous and 10 nonmucinous colorectal adenocarcinomas, 1 cloacogenic carcinoma, 12 colorectal adenomas and 4 samples of normal colorectal mucosa using monoclonal antibodies (MAbs)." (PMID 3028461, 1987).
dengue (1 paper, 2018). "In the present study best endogenous gene among COX, ACTB, GAPDH, HMBS, HPRT and B2M during dengue fever." (PMID 30071880, 2018). "The other genes selected namely COX and B2M are found to be upregulated while HMBS is downregulated in dengue, this differential expression of these genes during dengue infection eliminates their use as a candidate reference gene, supporting the findings of the present study." (PMID 30071880, 2018). "However, the poorly performing combination of COX, B2M and HMBS showed an inconsistent expression with a 2.12-fold increase in SD cases and 1.12-folds increase in All Dengue cases." (PMID 30071880, 2018).
disc degeneration (1 paper, 2019). "However, during an inflammatory response, the circulating levels of free B2M protein are known to increase and increased CSF levels of B2M have been observed in painful disc degeneration." (PMID 30770760, 2019).
E. coli (1 paper, 2022). "Association was revealed between B2M and reaction to cancer immunotherapies in multiple organs, however, investigations of the role of B2M in pathogenic E. coli infections are still limited." (PMID 35498757, 2022).
encephalitis (1 paper, 2013). An acute inflammatory process affecting the brain parenchyma. "Therefore, in disorders with cellular infiltration such as inflammation (especially encephalitis) or cancer cell invasion, B2M expression levels may be significantly varied compared with normal tissue." (PMID 23451040, 2013).
endothelial dysfunction (1 paper, 2023). In vascular diseases, endothelial dysfunction is a systemic pathological state of the endothelium (the inner lining of blood vessels) and can be broadly defined as an imbalance between vasodilating and vasoconstricting substances produced by (or acting on) the endothelium. "High levels of beta-2 microglobulin is associated with a high risk of cardiovasular disease through endothelial dysfunction." (PMID 37762225, 2023). "Endothelial dysfunction is present in pSS patients and is associated with a high focus score and activity as well as increased concentrations of antibodies, pro-inflammatory cytokines, and beta 2-microglobulin." (PMID 37762225, 2023). "Glandular inflammatory infiltrate (assessed by means of the focus score) was associated with increased serum levels of antibodies, proinflammatory cytokines, and beta-2 microglobulin, generating endothelial dysfunction." (PMID 37762225, 2023). "Endothelial dysfunction (expressed as FMD%) was correlated with focus score, ESSDAI, levels of anti-SSA and anti-SSB antibodies, beta-2 microglobulin, IL-6, and TNF-α, with statistical significance." (PMID 37762225, 2023).
enteritis (1 paper, 2011). Inflammation of the small intestine. "RPL4, HPRT1 and B2M are reported as stably expressed and suitable candidate genes in intestinal tissues collected from healthy pig and from pigs with enteritis." (PMID 22023805, 2011).
epilepsy (1 paper, 2024). A brain disorder characterized by episodes of abnormally increased neuronal discharge resulting in transient episodes of sensory or motor neurological dysfunction, or psychic dysfunction. "Thus, we speculate that B2m overexpression could be one of the mechanisms leading to epilepsy development." (PMID 38791067, 2024).
experimental autoimmune encephalomyelitis (1 paper, 2024). An autoimmune demyelinating disease of the central nervous system that is produced experimentally in animals by the injection of homogenized brain or spinal cord in Freund's adjuvant. "(G, I) Representative images of RNAscope labeling for (G) Fcgr3, B2m, Cd74, and (I) Gfap, C3 in Swiss Jim Lambert (SJL) mice 11 weeks after experimental autoimmune encephalomyelitis (EAE) induction." (PMID 39475792, 2024).
fibrosis (1 paper, 2017). the formation of excess fibrous connective tissue in an organ or tissue in a reparative or reactive process. "Proteins related to immune system processes, including Ig kappa chain c region, beta-2-microglobulin, Ifi441 and complement C4, were also found to be under-expressed in rats in the fibrosis model group." (PMID 28662027, 2017).
gallbladder cancer (1 paper, 2016). "However in patients with gallbladder cancer, B2M expression is significantly correlated with large tumour size, high TNM stage, lymph node metastasis and invasion of carcinomas." (PMID 26983758, 2016).
gingivitis (1 paper, 2025). A disorder involving inflammation of the gums; may affect surrounding and supporting structures of the teeth. "Beta-2-microglobulin may be an important salivary marker of compromised mucosal integrity in gingivitis, although some aspects of this association remain unclear." (PMID 40366920, 2025).
hypertensive nephropathy (1 paper, 2018). Kidney damage that results from chronically elevated blood pressure; complications include glomerular damage resulting in proteinuria and hematuria. "Three studies reported on the use of breviscapine injection plus antihypertensive drugs in the treatment of urine beta-2-microglobulin for hypertensive nephropathy." (PMID 30671127, 2018). "The present meta-analysis indicated that breviscapine injection can reduce 24-hour urinary protein and the urinary beta-2-microglobulin; a reduction in urinary protein may contribute towards the renal protective effect of breviscapine injection in patients with hypertensive nephropathy." (PMID 30671127, 2018).
hypoxic ischemic encephalopathy (1 paper, 2024). "While an elevation of B2M in infants with hypoxic ischemic encephalopathy has been demonstrated in one study, another provided evidence that B2M induces M2-like macrophage polarization and alters the tumor immune microenvironment toward an anti-inflammatory state." (PMID 38836960, 2024).
injury (1 paper, 2024). Damage inflicted on the body as the direct or indirect result of an external force, with or without disruption of structural continuity. "Increased B2M levels in the blood, and by contrast low levels in the urine, are indicative of glomerular dysfunction, PAI1 is induced in kidney injury, and has been suggested as a causative agent in CKD." (PMID 38347603, 2024).
iron deficiency (1 paper, 2012). "Additionally, mutations in the genes of human hemochromatosis protein (HFE) and its interacting protein beta-2 microglobulin (B2M), which play an important role in iron metabolism, cause murine iron deficiency." (PMID 22536488, 2012).
Keratoconjunctivitis sicca (1 paper, 2012). Dryness of the eye related to deficiency of the tear film components (aqueous, mucin, or lipid), lid surface abnormalities, or epithelial abnormalities. "Normal production of tear proteins, such as lysozyme, lactoferrin, lipocalin, and phospholipase A2 beta-2 microglobulin, is reportedly decreased in keratoconjunctivitis sicca." (PMID 23272196, 2012).
Klinefelter syndrome (1 paper, 2023). A sex chromosome disorder caused by the presence of an extra X chromosome in the male karyotype. "B2M, a gene involved in immune responses and apoptosis triggered by an elevation in antigen presentation, was found to be up-regulated in Klinefelter syndrome patients." (PMID 38012716, 2023).
laryngeal squamous cell carcinoma (1 paper, 2021). A squamous cell carcinoma that arises from the larynx. "Epstein–Barr virus DNA positivity, age ≥ 55 years, cigarette smoking, and high BCL-2, B2M, and CD161 expression were identified as independent risk factors for primary laryngeal squamous cell carcinoma." (PMID 33917480, 2021).
Lymphatic Metastasis (1 paper, 2021). Transfer of a neoplasm from its primary site to lymph nodes or to distant parts of the body by way of the lymphatic system. "Mutant B2M status (vs wt B2M) increased the log odds of peritoneal/peritoneal and lymphatic metastasis (vs non-peritoneal/peritoneal and lymphatic metastasis) by 3.873 (p=0.00968)." (PMID 34168989, 2021).
male infertility (1 paper, 2023). The inability of the male to effect fertilization of an ovum after a specified period of unprotected intercourse. "A total of five proteins (PFS males) have been used as potential markers of male infertility, namely B2M, complement-3 (C3), CFB, VNN2, and CTSS." (PMID 37969811, 2023).
Maturity-onset diabetes of the young (1 paper, 2020). "Maturity-onset diabetes of the young (MODY), a monogenic form of diabetes, can result from mutations in one of the genes expressed in β-cell that include GCK, HNF1A, HNF1B, HNF4A, PDX1, and B2M." (PMID 33113859, 2020).
melancholic depression (1 paper, 2016). "No mediation was found for IGFBP1, ACE and B2M (comparison atypical and melancholic depression) and B2M, ANG2 and VWF (comparison atypical depression and controls)." (PMID 27404283, 2016).
meningitis (1 paper, 2019). A disorder characterized by acute inflammation of the meninges of the brain and/or spinal cord. "B2M has the potential to aid in the early and accurate diagnosis of meningitis, which can result in more timely and appropriate antibiotic administration." (PMID 31063510, 2019). "Considering that there is not a negligible percentage of traumatic LPs in preterm infants, we conclude that the level of B2M in CSF may be an effective ancillary tool for diagnosing meningitis in the preterm population." (PMID 31063510, 2019).
metastasis (1 paper, 2021). The spread or migration of cancer cells from one part of the body (where they first appeared) to another. "B2M-mutant tumor patients predominantly presented with peritoneal metastases, with 2 patients having exclusively peritoneal and 2 patients with peritoneal and lymph node metastases, in contrast to only one patient with a singular hepatic metastasis." (PMID 34168989, 2021).
MHC class I deficiency (1 paper, 2025). "Autosomal recessive mutations in TAP1, TAP2, TAPBP, or B2M, are associated with major histocompatibility complex (MHC) class I deficiency." (PMID 41298860, 2025).
multinodular goiter (1 paper, 2019). Nodular goiter characterized by more than one discrete tissue mass. "The expression characteristics of 12 candidate reference genes (GAPDH, ACTB, HPRT1, TBP, B2M, PPIA, 18SrRNA, HMBS, GUSB, PGK1, RPLP0, and PGM1) were assessed by qRT-PCR in 45 thyroid tissue samples (15 papillary thyroid carcinoma, 15 paired normal tissues and 15 multinodular goiters)." (PMID 31645594, 2019).
Mycobacterium infection (1 paper, 2014). Infections with bacteria of the genus Mycobacterium. "The deficiencies in HFE and beta-2 microglobulin are known to raise the susceptibility to Mycobacterium infection." (PMID 25544913, 2014).
myxoid liposarcoma (1 paper, 2015). A liposarcoma characterized by the presence of round non-lipogenic primitive mesenchymal cells and small signet ring lipoblasts within a myxoid stoma with a branching vascular pattern. "We could identify B2M and IPO8 as suitable reference genes for myxoid liposarcoma and fat control samples in cryo-conserved as well as in formalin-fixed tissue." (PMID 26036639, 2015).
nephrotic syndrome (1 paper, 2025). A collection of symptoms that include severe edema, proteinuria, and hypoalbuminemia; it is indicative of renal dysfunction. "Nephrotic syndrome, associated with urinary loss of anticoagulantfactors (e.g., antithrombin, protein S), immunomodulatory drug use, high freelight chain levels, and elevated beta-2 microglobulin levels, collectivelyincrease thromboembolic risk." (PMID 40160592, 2025).
nephrotoxicity (1 paper, 2024). Toxicity that causes injury to the kidney or damages its function. "Increased urinary beta-2 microglobulin and blood gamma-glutamyl transferase could be markers of early paracetamol nephrotoxicity." (PMID 38956487, 2024).
neurofibroma (1 paper, 2017). An intraneural or extraneural neoplasm arising from nerve tissues and neural sheaths. "In contrast, the expression of the necessary MHC Class I-associated protein β-2-microglobulin (B2M) is up-regulated among neurofibromas." (PMID 29137242, 2017). "Benign neurofibromas with nodular histology demonstrated the highest average of B2M staining scores of all samples tested, while the diffuse neurofibromas exhibited the lowest average B2M scores." (PMID 29137242, 2017). "The HLA-A/B/C score correlated with B2M expression for MPNST samples but not individual benign neurofibroma subtypes." (PMID 29137242, 2017).
nonalcoholic steatohepatitis (1 paper, 2020). "Additionally, in the nonalcoholic steatohepatitis (NASH) model, the YWHAZ and ACTB genes were found to be the most stable and the CYC1 and B2M genes were the least stable." (PMID 32089674, 2020).
oral lichen planus (1 paper, 2024). Oral lichen planus is a chronic inflammatory oral condition of unknown aetiology characterized by T-cell-mediated chronic immune response and abnormal epithelial keratinization cycle. "Elevated salivary B2m levels have been observed in patients with oral lichen planus compared to healthy group, and increased B2m secretion activated fibroblast, contributing to the cardiac repair postischemia." (PMID 39169434, 2024).
ovarian serous tumor (1 paper, 2014). A benign, borderline, or malignant epithelial tumor of the ovary characterized by the presence of neoplastic epithelial cells that, in well differentiated tumors, resemble the epithelial cells of the fallopian tube and, in poorly differentiated tumors, show anaplastic features. "ACTB, PPIA, RPL13A, RPLP0, TBP, and B2M achieved high expression stability, which suggested that they were adequate for normalizing gene expression data among ovarian serous tumors." (PMID 24776823, 2014).
Paraproteinemia (1 paper, 2014). An abnormal immunoglobulin or part of an Ig (light chain) in the circulation. "Other previously discussed risk factors evaluated, e.g. elevated beta-2-microglobulin, plasmacytic differentiation, exact localisation of OAML (i.e. lacrimal gland, conjunctival or intraorbital) and presence of paraproteinemia also did not affect the prognosis in our cohort of patients." (PMID 25077481, 2014).
parasitemia (1 paper, 2021). "Mhc1-/- and b2m-/- mice showed similar parasitemia levels as compared to their WT controls." (PMID 34587172, 2021).
periodontitis (1 paper, 2025). An acute or chronic inflammatory process that affects the tissues that surround and support the teeth. "In saliva, the most differentially expressed protein was beta-2-microglobulin, which was approximately 44 times more abundant in patients with periodontitis than in healthy subjects." (PMID 40384977, 2025).